GRIN2B (glutamate ionotropic receptor NMDA type subunit 2B)
Diseases named in the same sentence as GRIN2B in open-access papers (continued):
Sharing a sentence is not in itself a finding about the gene and the disease.
alcoholism (7 papers, 2013 to 2022). "Of note, GRIN2B was linked to left posterior cingulate volume in adolescents with alcohol dependence, one of the disorders most closely related to impulsivity." (PMID 34440367, 2021). "In addition, smokers who carried the risky allele on GRIN2B tended to have an early alcoholism onset than those on DRD3 (rs2134655)." (PMID 28512340, 2017). "Importantly, we are the first to report SNPs associated with unequal age-of-onset distributions for susceptible cases to alcoholism [rs172677 on GRIN2B (p = 0.013), rs1439047 on NTRK2 (p = 0.005), rs63319 on ALDH1A1 (p = 0.033), and rs1079597 on DRD2 (p = 0.028)]." (PMID 28512340, 2017). "The cluster of DRD2 and GRIN2B share the alcoholism pathway with NTRK2 (rs1439047) and have the same pathways of neuroactive ligand–receptor interaction and dopaminergic synapse as does DRD3 (rs2134655)." (PMID 28512340, 2017). "Thus, the mechanism underlying ALDH1A1-related alcoholism is different from the gene cluster of DRD2, DRD3, GRIN2B, and NTRK2, which is directly involved in behavioural rewarding effects of alcohol consumption." (PMID 28512340, 2017). "Especially, alcoholism (hsa05034) pathway exhibits the highest number of target connections (degree = 12), which includes consequential target genes such as MAOA, GRIN2A, GRIN2B, and CALM1." (PMID 32182911, 2020).
glioma (7 papers, 2013 to 2025). A benign or malignant brain and spinal cord tumor that arises from glial cells (astrocytes, oligodendrocytes, ependymal cells). "The neurotransmitter glutamate, which mediates synaptic transmission through the N-methyl-D-aspartate glutamate receptors 2A and 2B (GRIN2A and GRIN2B) that appear in the PCST network, can promote glioma cell growth, and this pro-proliferative effect in U87MG cells is due to EGFR signaling." (PMID 23408876, 2013).
mood disorder (7 papers, 2014 to 2025). A cognitive disorder a disturbance in which the person's mood is hypothesized to be the main underlying feature. "Pharmacologically, GluN2B-selective negative allosteric modulators such as radiprodil normalise the gain-of-function currents produced by pathogenic GRIN2B mutations and are being repositioned for mood disorders." (PMID 41373485, 2025).
obsessive-compulsive disorder (7 papers, 2013 to 2024). A disorder characterized by the presence of persistent and recurrent irrational thoughts (obsessions), resulting in marked anxiety and repetitive excessive behaviors (compulsions) as a way to try to decrease that anxiety. "In patients with obsessive compulsive disorder (OCD), reported GRIN2B SNPs to be associated with total thalamus volume." (PMID 34440367, 2021).
dementia (6 papers, 2017 to 2024). Loss of intellectual abilities interfering with an individual's social and occupational functions. "Future longitudinal follow-up in larger populations will bring insights of whether GRIN2B gene variation might be a potential indicator for cognitive reserve or may serve as a risk-factor for late onset dementia." (PMID 28439047, 2017).
dyslexia (6 papers, 2010 to 2025). A learning disorder characterized by an impairment in processing written words. "Zinc, a trace element that plays an important role in neurological disorders, was associated with dyslexia risk mediated by the GRIN2B gene polymorphism rs1805502." (PMID 39020327, 2024). "GRIN2B was selected for the current study because it lies in a region with evidence of linkage for a phonological non-word memory trait in the UW cohort and was associated with verbal memory phenotypes in two European dyslexia datasets." (PMID 40424442, 2025). "GRIN2B is a candidate gene for the chromosome 12p12 locus for phonological memory identified in our American dyslexia sample; the variant rs1012586 was significantly associated with phonological memory in a German dyslexia sample." (PMID 23308072, 2012). "Among the top 20 genes with the highest priority DRD2, DRD4, CNTNAP2 and GRIN2B are mentioned in the literature as directly linked with the comorbidity of ADHD and dyslexia." (PMID 37667328, 2023). "Upon comparing whether dyslexia risk genes were also susceptibility genes for other neurodevelopmental conditions, such as ASD, ADHD and ID, we found that the GRIN2B gene was a susceptibility gene for these three conditions." (PMID 39020327, 2024). "This region contains glutamate receptor, ionotropic, N-methyl-D-aspartate 2B (GRIN2B, MIM:13249), a gene that had support as a dyslexia candidate gene from studies in other data sets." (PMID 40424442, 2025). "We present additional evidence for a role in dyslexia risk for DCDC2, KIAA0319, GRIN2B and CYP19A1, but not for DNAAF4." (PMID 40424442, 2025).
glaucoma (6 papers, 2013 to 2024). Increased pressure in the eyeball due to obstruction of the outflow of aqueous humor. "In our study, we examine the relationship between single nucleotide polymorphisms (SNPs) of APOE (rs449647), BDNF (rs2030324), GRIN2B (rs3764028), and HSP70-1 (rs1043618) genes and the possible occurrence risk of primary open angle glaucoma in the Polish population." (PMID 25893192, 2015). "These 13 glaucoma-associated genes can be divided into three functional groups: phototransduction-related genes (GNGT1, OPN1SW, PDE6A, PDC, CRX, CNGB1, GUCY2F), glutamate receptor (GR) genes (GRIN2B, GRIK3, GRIK4), and 5-hydroxytryptamine receptor (HTR) genes (HTR1A, HTR1E, HTR7)." (PMID 33874942, 2021).
psychosis (6 papers, 2015 to 2025). "Levels of EV-secreted miRNA-223 were increased in the orbitofrontal cortex of post-mortem brain samples from patients with SCZ and patients with BD with psychosis, and an inverse association was observed with the expression of the targets of miRNA-223, GRIN2B and GRIA2." (PMID 36302978, 2023). "Here we show that miR-223, a known exosome-enriched miRNA, is significantly increased in the OFC of subjects with SCZ and BD with psychosis, and is negatively correlated to the mRNA levels of its targets GRIN2B and GRIA2, which are also significantly downregulated." (PMID 31775160, 2020). "Our results showed that BD patients with psychosis but not BD patients without psychosis displayed significant increases in SERPINA3, and reductions in GRIN2B, GRIA2, and ADAR2 mRNAs, similar to those seen in SCZ." (PMID 31775160, 2020).
systemic lupus erythematosus (6 papers, 2017 to 2026). An autoimmune multi-organ disease typically associated with vasculopathy and autoantibody production. "Grin2b was found to be involved in seven pathways, such as long-term potentiation, glutamatergic synapse, amphetamine addiction, neuroactive ligand–receptor interaction, systemic lupus erythematosus, circadian entrainment, and dopaminergic synapse." (PMID 41150532, 2025).
diabetes (5 papers, 2014 to 2024). "The results of this study indicate that the core genes (CNOT6L and GRIN2B) are associated with diabetes, T2D, diabetic complications, abnormal blood lipids, high blood sugar, and inflammation." (PMID 39433858, 2024). "In addition, statistical analysis demonstrated that the polymorphisms of APOE, BDNF, GRIN2B, and HSP70-1 genes are not related with hypertension, diabetes, low blood pressure, and vascular disease." (PMID 25893192, 2015).
Hyperglycemia (5 papers, 2015 to 2024). An increased concentration of glucose in the blood. "We found that the core genes (CNOT6L and GRIN2B) are associated with type 2 diabetes, diabetic complications, dyslipidemia, hyperglycemia, and inflammation." (PMID 39433858, 2024). "However, the conditional deletion of Grin2b from AgRP neurons in ob/ob mice leads to a complete prevention of hyperglycemia-induced by the lack of leptin signaling, independently of changes in body weight and food intake." (PMID 32823489, 2020).
nicotine addiction (4 papers, 2015 to 2023). "GRIN2B is also associated with nicotine dependence and is one of the genes influencing smoking behaviors." (PMID 37686494, 2023). "Specifically, GRIN2B was enriched in three pathways, including the Ras signalling pathway, cAMP signalling pathway, and nicotine addiction." (PMID 29785036, 2018). "In addition to KMT2C, miR‐3157‐5p, miR‐6808‐5p, and miR‐6874‐3p also target GRIN2B, which belongs to the amphetamine and nicotine addiction pathways." (PMID 35032098, 2022).
developmental and epileptic encephalopathy (3 papers, 2021 to 2025). An epilepsy associated with developmental impairment that may be due to either the underlying etiology or the superimposed epileptic activity, or both. "GRIN2B is related to intellectual developmental disorder, autosomal dominant 6, with or without seizures (MIM #613970), and developmental and epileptic encephalopathy 27 (MIM #616139)." (PMID 34858471, 2021).
type 2 diabetes (3 papers, 2021 to 2024). "Kochetova el at found that GRIN2B is a significant biomarker for type 2 diabetes compared to healthy controls, but it was confirmed for the first time in our study that GRIN2B expression in T1D indicates a good prognosis." (PMID 33827531, 2021).
Ataxia (2 papers, 2015 to 2022). Ataxia refers to impaired coordination of voluntary muscle movement. "Compared to the uninjured mice, we found that the mRNA expression levels of Gria3, Gria4, Grin2b, and Grin2c were markedly increased in DCN at day 7 post-SNC in non-ataxia control and ataxia mice." (PMID 36064798, 2022).
Dravet syndrome (2 papers, 2016 to 2021). "These ASD genes included the Dravet syndrome gene SCN1A and the Timothy syndrome gene CACNA1C, but also GRIN2B, HTR2A, PCDH9, and other genes." (PMID 34188164, 2021).
melanoma (2 papers, 2014 to 2018). A malignant, usually aggressive tumor composed of atypical, neoplastic melanocytes. "The existence of mutations in glutamate receptors was described in prior exome sequencing studies, and our data not only confirmed that GRIN2A was mutated in melanoma (5 out of 28 cases) but also showed that GRIN2B was recurrently mutated." (PMID 25393105, 2014). "Our in silico significance and proximity analysis of 28 paired cases (13 WGS and 15 targeted cases) identified known (e.g., BRAF, NRAS, CDKN2A, and GRIN2A) and novel (e.g., EPHA3, GRIN2B, and ASXL3) genes involved in melanoma." (PMID 25393105, 2014).
non-small cell carcinoma (2 papers, 2011 to 2014). "Aberrant methylation status of NR2B promoter was present in more than 60 % of human gastric and non-small cell lung carcinoma samples, whereas the GRIN2B methylation status alterations were found in no more than 5 % of corresponding normal tissues." (PMID 24610491, 2014).
absence seizures (1 paper, 2025). "We show that Grin2b+/− rats displayed a higher prevalence of absence seizure SWDs, which had increased delta spectral power, throughout both light and dark phases of the 24‐h cycle." (PMID 40827489, 2025). "Compared to wild‐type rats, Grin2b+/− rats had a higher incidence of spontaneous spike and wave discharges (SWDs), the electrographic correlate of absence seizures." (PMID 40827489, 2025). "Grin2b+/− rats displayed spontaneous behavioral arrests reminiscent of absence seizures in patients." (PMID 40827489, 2025). "We show that Grin2b+/− rats had a higher number of absence seizures." (PMID 40827489, 2025).
Cirrhosis (1 paper, 2026). A chronic disorder of the liver in which liver tissue becomes scarred and is partially replaced by regenerative nodules and fibrotic tissue resulting in loss of liver function. "Notably, gene hubs like Drd1, Gria1‐4, Grin1, Grin2b, Grm5, and GABAα receptor genes were also highly connected, mirroring gene expression patterns observed in liver fibrosis, cirrhosis, and hepatocellular carcinoma (HCC)." (PMID 41508419, 2026).
colon cancer (1 paper, 2025). "In colon cancer, GRIN2B is related to colon cancer and the endoplasmic reticulum response." (PMID 40452916, 2025).
COVID-19 (1 paper, 2022). A disease caused by infection with severe acute respiratory syndrome coronavirus 2. "We suggested that the six antihistamines (Loratadine, Fexofenadine, Triprolidine, Ebastine, Dimetindene, and Terfenadine) played a critical role in COVID-19 by affecting the GRIN2B target as well as inhibiting neuroactive ligand–receptor interaction (KEGG ID: hsa04080)." (PMID 35723367, 2022). "Therefore, the hub mechanism of antihistamines against COVID-19 might be to inhibit GRIN2B on the neuroactive ligand–receptor interaction by Loratadine as an antagonist." (PMID 35723367, 2022). "Furthermore, GRIN2B with the highest degree of value in PPI network, with the highest Betweenness Centrality (BC) in topological analysis, and correlated with neuroactive ligand–receptor interaction was considered as a core target of antihistamines in COVID-19." (PMID 35723367, 2022).
demyelinating disease (1 paper, 2019). A broad group of disorders that affect the myelin sheaths that cover the neurons. "GRIN2B is suggested as an important target gene of circRNAs in immune-mediated demyelinating diseases because it is regulated by circRNAs and promotes disease." (PMID 31611906, 2019).
emotional instability (1 paper, 2016). "The emotional instability significantly differed in individuals carrying the GRIN1 (rs4880213) and GRIN2B (rs7301328) polymorphisms." (PMID 26819771, 2016).
hypothyroidism (1 paper, 2022). Abnormally low levels of thyroid hormone. "Our results showed a pronounced reduction in serum GRIN2B in patients with postoperative hypothyroidism by 3.45-fold compared with the controls." (PMID 35186144, 2022). "Even so, a probable increase in GRIN2B levels by 1.58-fold compared with controls was observed along with AIT-induced hypothyroidism." (PMID 35186144, 2022). "In our study, GRIN2B levels were significantly decreased in patients with postoperative hypothyroidism (3.45 times)." (PMID 35186144, 2022). "On the other hand, there was a probable increase in GRIN2B levels in patients with AIT-induced hypothyroidism by 1.58 times compared with controls." (PMID 35186144, 2022). "Moreover, there was a probable increase in GRIN2B levels in patients with AIT-induced hypothyroidism by 1.58 times compared with controls." (PMID 35186144, 2022). "GRIN2B levels were significantly decreased in patients with postoperative hypothyroidism 3.45 times, and in patients with AIT-induced hypothyroidism, there was a probable increase in GRIN2B levels by 1.58 times compared with controls." (PMID 35186144, 2022). "At the same time, in patients with AIT without hypothyroidism, the level of GRIN2B was not significantly different from the control group." (PMID 35186144, 2022). "In addition, our study identified that in patients with AIT without hypothyroidism, the level of GRIN2B was not markedly different from the controls." (PMID 35186144, 2022).
invasive breast carcinoma (1 paper, 2022). A carcinoma that infiltrates the breast parenchyma. "Tumor samples with GRIN2B high expression were associated with poor prognosis in invasive breast cancers." (PMID 36139568, 2022). "Moreover, in breast invasive carcinomas, GRIN2B and GRIN3B are two GRIN genes mostly expressed." (PMID 36139568, 2022).
kidney cancer (1 paper, 2021). Primary or metastatic malignant neoplasm involving the kidney. "More unexpected and presumably novel genes of interest include for instance, GRIN2B—a gene encoding for a subunit of a N-methyl-D-aspartate (NMDA) receptor family member—is a source-level core gene for both breast and kidney cancer." (PMID 34115745, 2021).
myopia (1 paper, 2026). "ATF3, GRIN2B, and GSTM3 have emerged as promising oxidative stress-related biomarkers with significant potential for understanding myopia pathology." (PMID 41912634, 2026).
myopic macular degeneration (1 paper, 2025). "Current research suggests that CCDC102B is primarily involved in the development of myopic macular degeneration and tumorigenesis, while GRIN2B is mainly involved in neurotransmitter transmission." (PMID 39854306, 2025).
nematode infection (1 paper, 2019). "Two sub-units of NMDARS, NR2A and NR2B (also known as Grin2A and Grin2B) as well as several AMPARs including the metabotropic glutamate receptors 1 and 2 (mGlu-R1 and mGlu-R2), Gria3, Grm2, Grm4, Grik3 and Grik5 were up-regulated in the pup brain on P7 in response to maternal nematode infection." (PMID 30862816, 2019). "In response to maternal nematode infection, expression of both NR2A and NR2B (also known as Grin2A and Grin2B) genes was higher in the P7 brain." (PMID 30862816, 2019).
oesophageal cancer (1 paper, 2018). "GRIN2B is epigenetically inactivated and supresses oesophageal cancer activity." (PMID 29785036, 2018).
preeclampsia (1 paper, 2023). Preeclampsia is a hypertensive disorder of pregnancy that is characterized by new-onset hypertension with proteinuria presenting after 20 weeks of gestation, and depending on mild or severe forms may initially present with severe headache, visual disturbances, and hyperreflexia. "Among them, the CNR1 and GRIN2B genes, encoding cannabinoid receptor 1 and NMDA-type ionotropic glutamate receptor subunit 2B, respectively, have been associated with the risk of preeclampsia in case-control studies." (PMID 36768581, 2023).
pulmonary hypertension (1 paper, 2014). Increased pressure within the pulmonary circulation due to lung or heart disorder. "These genes, such as PLA2G12A, RGCC, C9ORF3, GRIN2B, GRID1 and EPAS1, are involved in high-altitude physiology including angiogenesis, pulmonary hypertension, oxygen intake, defense response and erythropoiesis." (PMID 25270331, 2014). "Many genes are functionally related to high-altitude physiology, such as angiogenesis (RGCC), pulmonary hypertension remodeling (PLA2G12A), oxygen intake (C9ORF3), neural response (GRID1 and GRIN2B), melanin synthesis (MITF, PDGFRB and PIK3R3) and heart development (FOXS1, GAA and MYLK2)." (PMID 25270331, 2014).
Sotos syndrome (1 paper, 2023). Sotos syndrome is a rare multisystemic genetic disorder characterized by a typical facial appearance, overgrowth of the body in early life with macrocephaly, and mild to severe intellectual disability. "Exceptions were apparent; for example, growth was a better predictor for NSD1, while development was a better predictor for GRIN2B (Sotos syndrome MIM: 117550; GRIN2B MIM: 138252)." (PMID 36561149, 2023).
thyroid (1 paper, 2022). "In the present study, we examined the NMDA gene polymorphism (rs4880213) and the GRIN2B blood serum levels in patients with thyroid pathology in the population of Western Ukraine." (PMID 35186144, 2022). "In a more detailed analysis of GRIN2B levels in patients of different groups, the indicators significantly differed depending on thyroid pathology." (PMID 35186144, 2022). "GRIN2B levels were significantly different in patients of different groups depending on thyroid pathology." (PMID 35186144, 2022). "In our study, GRIN2B levels were significantly different in patients of different groups depending on thyroid pathology: a pronounced decrease in serum GRIN2B in patients experiencing PO 3.45 times compared to the control group." (PMID 35186144, 2022).
tubulinopathy (1 paper, 2018). A nervous system disorder characterized by complex cortical malformations including in most cases dysmorphic basal ganglia and/or corpus callosum in which the cause of the disease is a variation in a tubulin gene. "The patients demonstrated an extensive bilateral cortical malformation similar in appearance to tubulinopathy- or GRIN2B-associated dysgyria." (PMID 29365063, 2018).